SIRT1 (sirtuin 1)
Diseases named in the same sentence as SIRT1 in open-access papers (continued):
Sharing a sentence is not in itself a finding about the gene and the disease.
medulloblastoma (6 papers, 2014 to 2025). A malignant, invasive embryonal neoplasm arising from the cerebellum. "Studies have shown SIRT1 expression in a substantial percentage of medulloblastoma tissues, suggesting its involvement in tumor development and progression." (PMID 40710366, 2025). "Inhibiting SIRT1 expression or activity leads to cell cycle arrest and increased apoptosis in medulloblastoma cells." (PMID 40710366, 2025). "Resveratrol can reduce SIRT1 expression in medulloblastoma cells at both transcriptional and translational levels without affecting its enzymatic activity." (PMID 40710366, 2025). "In human medulloblastoma cells, SIRT1 expression patterns have also been correlated with their formation and prognosis." (PMID 32158616, 2020). "BCOR suppresses the tumor progression of SHH medulloblastoma by a BCL6/BCOR/SIRT1 complex that induces epigenetic repression of GLI1 and GLI2." (PMID 27825128, 2016). "The conclusion is that high levels of SIRT1 expression may promote the formation of medulloblastoma, and resveratrol could be a potential therapeutic agent for it by regulating SIRT1 expression without affecting its activity." (PMID 40710366, 2025). "SIRT1 also plays a significant role in medulloblastoma, influencing cell growth and survival." (PMID 40710366, 2025). "Notably, SIRT1 expression is higher in aggressive subtypes of medulloblastoma (large cell/anaplastic—79.07% and classic medulloblastomas—60.29%) compared with less aggressive ones (nodular/desmoplastic subtype—22.22%), indicating a potential link between SIRT1 and tumor aggressiveness." (PMID 40710366, 2025).
nasopharyngeal carcinoma (6 papers, 2019 to 2025). A carcinoma arising from the nasopharyngeal epithelium. "In a study by Jiang and colleagues, the treatment of nasopharyngeal carcinoma with 40 μM EGCG induced apoptosis through the downregulation of Sirtuin 1 (SIRT1)." (PMID 39272454, 2024). "In this study, we are the pioneers to report that EGCG-induced apoptosis in nasopharyngeal carcinoma CNE-2 cells by inhibiting the expression and activity of SIRT1." (PMID 35548580, 2022). "EGCG inhibited the growth and proliferation of nasopharyngeal carcinoma (CNE‐2 and 5‐8F) cells by inducing apoptosis (cell death) through the downregulation of an NAD+‐dependent protein deacetylase, sirtuin 1 (SIRT1) that plays an important role in cancer cell metabolism." (PMID 40255557, 2025). "Also, in nasopharyngeal carcinoma, EGCG induces apoptosis through downregulation of Sirtuin 1 (SIRT1) when used at 40 μM." (PMID 38543009, 2024).
necrotizing enterocolitis (6 papers, 2020 to 2025). Necrotizing enterocolitis (NEC) is a devastating disease that affects mostly the intestine of premature infants. "Sirtuin 1- related pathways have been implicated in the protective effect of the probiotic Saccharomyces boulardii regarding necrotizing enterocolitis." (PMID 34072556, 2021). "Meanwhile, NR has been shown to significantly alleviate intestinal MEC dysfunction by activating the SIRT1-eNOS pathway and reducing ROS production under inflammatory conditions such as TNFα stress and necrotizing enterocolitis." (PMID 39598406, 2024). "Sirtuin 1 was reported to regulate the gut microbiota, sirtuin 2 was found to maintain gut homeostasis, while sirtuin 1 is supposed to be involved in the pathophysiology of necrotizing enterocolitis." (PMID 34072556, 2021). "Additionally, the gut microbiome possesses the capacity to affect sirtuin-associated pathways; for example, Saccharomyces boulardii has been demonstrated to alter necrotizing enterocolitis through the modulation of the SIRT1/NF-κB signalling pathway and the intestinal microbiota." (PMID 40136715, 2025). "The relationship between Sirtuin1 or Silent mating–type information regulation 2 homolog-1 (SIRT1) and transforming growth factor-β1 (TGF-β1) protein expression and clinical features in mucous layer of post-necrotizing enterocolitis stricture tissues." (PMID 35958178, 2022).
non-alcoholic fatty liver (6 papers, 2010 to 2024). A benign form of fatty non-alcoholic fatty liver disease where the disease has not yet progressed to the inflammation of liver. "Maslinic acid, a pentacyclic triterpene acid in CP, has been shown to protect against nonalcoholic fatty liver through the Sirt1/AMPK pathway in mice." (PMID 38890862, 2024). "In addition, CK2-mediated phosphorylation of SIRT1 at the Ser164 site inhibits its nuclear localization and promotes the progress of non-alcoholic fatty liver, which provides evidence that SIRT1 is involved in the improvement of metabolic diseases." (PMID 34616289, 2021). "PPARγ, which may be regulated by SIRT1, is thought to be involved in the development of alcoholic and nonalcoholic fatty liver." (PMID 21087523, 2010).
ovarian tumors (6 papers, 2014 to 2024). "Mammalian silent information regulator 1 (SIRT1) is reported to play a role in cancers of the secretory organs, including thyroid, pancreatic endocrine, and ovarian tumors." (PMID 30319549, 2018). "Thus, both AMPK and SIRT1, the two energy regulated enzymes are modulated by various dietary conditions in the ovarian tumors." (PMID 25026276, 2014). "Additionally, cytoplasmic SIRT1 may contribute to the formation and survival of polypoid giant tumor cells, leading to paclitaxel resistance in ovarian tumors." (PMID 39403142, 2024). "Thus it can be extrapolated that the upstream metabolic sensors like AMPK and SIRT1 maybe acting mainly through inhibition of mTOR, which results in deacceleration of ovarian tumor progression." (PMID 25026276, 2014). "MHY2245, an inhibitor of SIRT1, suppresses the PKM2/mTOR axis, stimulating autophagy and accelerating apoptosis, which leads to growth reduction in ovarian tumors." (PMID 39403142, 2024). "Resveratrol, a well-known potent activator of SIRT1, has been shown to increase mitochondrial numbers by activating the SIRT1/PGC-1α pathway and inhibit VEGF induction through HIF-1α in ovarian tumor cells under hypoxic conditions." (PMID 34381712, 2021).
renal carcinoma (6 papers, 2017 to 2025). A carcinoma arising from the epithelium of the renal parenchyma or the renal pelvis. "Furthermore, lactate treatment, at similar concentrations to those used in the current study, induced EMT, cell migration, and invasion in renal carcinoma cells by downregulating SIRT1 expression." (PMID 40507273, 2025). "In our study, the functional experiments indicated that knockdown of SIRT1 could promote the proliferation and migration of renal cancer cells, which further revealed that SIRT1 might act as an oncogene in renal cancer." (PMID 35252011, 2022). "Significantly, the inhibited effect of MOF overexpression on the proliferation and migration of renal cancer cells could be rescued by SIRT1 knockdown." (PMID 35252011, 2022). "Out of the unique set of genes detected by BNNPT, a few were reported to be relevant to renal cancer or disease: CDCP1, GSTT1, E2F3, MAPK1, SALL4, SIRT1, ADAMTS13, Gfrα1, ASPH, MIR17HG, APOE, BMP4, RCOR1, NUMB and SEC63." (PMID 28986523, 2017).
uveitis (6 papers, 2015 to 2022). An inflammatory process affecting a part of or the entire uvea. "Resveratrol, a well-known SIRT1 activator was able to decrease inflammation in endotoxin induced uveitis in mice by upregulating SIRT1 activity in the RPE57." (PMID 26619957, 2015). "Sirtuin 1 (Sirt1), a histone deacetylase, which could inhibit NF-κB transcription and T-cell proliferation, promote TNF-α induced apoptosis and affect immune tolerance through regulating histone acetylation, was considered as a risk factor for BD with uveitis." (PMID 38983559, 2022). "By feeding resveratrol to endotoxin-induced uveitis mice with lipopolysaccharide-induced uveitis, a study team found that resveratrol could significantly enhance the expression of Sirt1 gene in retinal pigment epithelial cells and choroid, and inhibit the occurrence of ocular inflammation." (PMID 34676209, 2021).
varicocele (6 papers, 2021 to 2025). A condition characterized by the dilated tortuous veins of the spermatic cord with a marked left-sided predominance. "Another study conducted on a rat-model concluded that testicular damage caused by varicocele is associated with OS, DNA damage, and increased miR-34 expression along with suppression of SIRT1/FOXO axis." (PMID 41283253, 2025). "Mostefa and colleagues reported an SIRT1 deficiency, and increased oxidative stress, as causes of male infertility in patients with varicocele." (PMID 35055159, 2022). "As varicocele also causes oxidative stress; however, the deficiency of SIRT1 has added effect of decreased seminal antioxidant defenses." (PMID 34746831, 2021). "Thus, the presence of varicocele associated with a SIRT1 deficiency amplifies DNA damage and causes infertility." (PMID 35055159, 2022). "The upregulation of SIRT1 activity modulated by M.S in the experimental group implies a potential molecular interplay between M.S and SIRT1 in varicocele-triggered OS, accompanied by increased FOXO1 expression and antioxidant capabilities." (PMID 40524181, 2025). "The present study revealed a significant reduction in the expression of SIRT1 and FOXO1 genes in the varicocele group, demonstrating an association with the level of ROS." (PMID 40524181, 2025). "The reduction in SIRT1/FOXO1 testicular expression levels in the varicocele group suggests a correlation between varicocele-related fertility disorders and the SIRT1/FOXO1/OS axis." (PMID 40524181, 2025). "A link has been found between the reduced expression of SIRT1 in the varicocele group and elevated levels of acetylated NF-κB, which can be attributed to compromised mitochondrial biogenesis, heightened OS, and increased inflammatory responses." (PMID 40524181, 2025). "Patients with OAT, particularly when resulting from varicocele, also present a lower expression of SIRT1 in the seminal fluid than fertile men." (PMID 40422880, 2025). "A case-controlled study reported a lower seminal expression of SIRT1 in patients with oligoasthenoteratozoospermia (especially in those with varicocele), compared to fertile men." (PMID 35055159, 2022). "The same group of researchers subsequently showed increased levels of SIRT1 after varicocele surgical repairs and, interestingly, these levels correlated positively with sperm concentrations, motility, and normal morphology." (PMID 35055159, 2022). "Indeed, SIRT1 has antioxidant effects, whereas varicocele leads to oxidative stress." (PMID 35055159, 2022). "The molecular mechanism by which antioxidants derived from M.S alleviate varicocele involves modulation of SIRT1, FOXO1, and pro-inflammatory mediators; addressing oxidative stress and inflammation—key contributors to varicocele pathogenesis." (PMID 40524181, 2025). "In essence, this study demonstrated notable alterations in SIRT1, FOXO1, NRF2, NF-κB, and TGF-β gene expression, and in OS levels in rats induced by varicocele, which aligns with the findings of previous studies." (PMID 40524181, 2025). "The enzymatic activities of SIRT1, FOXO1, and TGF-β were significantly reduced in the testes following the development of experimental varicocele." (PMID 40524181, 2025).
cholangiocarcinoma (5 papers, 2018 to 2025). A carcinoma that arises from the intrahepatic biliary tree (intrahepatic cholangiocarcinoma) or from the junction, or adjacent to the junction, of the right and left hepatic ducts (hilar cholangiocarcinoma). "Secreted CCL3 from hepatocytes, enhances cancer spread by triggering VIRMA and its key downstream target SIRT1, which drives the metastasis of intrahepatic cholangiocarcinoma." (PMID 39941858, 2025). "Canagliflozin treatment upregulated nicotinamide phosphoribosyltransferase (NAMPT), NAD+, and sirtuin 1 in cholangiocarcinoma and activated the NAD+ salvage pathway." (PMID 39940750, 2025). "This study investigated the anti-tumor effects of canagliflozin on cholangiocarcinoma and the effects of nicotinamide adenine dinucleotide (NAD)+ salvage pathway activation and sirtuin 1 on tumor growth." (PMID 39940750, 2025). "FOXO1 silencing or Sirt1 inhibition, affected autophagic flux, impaired mitochondrial function and induced apoptosis in a cholangiocarcinoma cell line, suggesting a role of Sirt1/FOXO1 pathway in the interplay between autophagy and mitochondrial dysfunction in CCA." (PMID 32138158, 2020).
chondrosarcoma (5 papers, 2017 to 2022). A malignant cartilaginous matrix-producing mesenchymal neoplasm arising from the bone and soft tissue. "Kaplan-Meier survival curves revealed that positive SIRT1 expression was associated with poor prognosis in patients with pelvis chondrosarcoma." (PMID 28112277, 2017). "Significant associations were observed between SIRT1 expression and the size of tumor, recurrence, metastasis and pathological type (P = 0.004, P = 0.008, P = 0.023, P = 0.002, respectively) for the 34 patients with pelvis chondrosarcoma." (PMID 28112277, 2017). "We also detected the underlying mechanism of SIRT1 in regulating chondrosarcoma cells metastasis." (PMID 28112277, 2017). "Resveratrol induces chondrosarcoma cell apoptosis via a SIRT1-activated NF-κB deacetylation and exhibits antichondrosarcoma activity in vivo." (PMID 35386302, 2022). "They demonstrated that resveratrol treatment induces apoptosis, prevents proliferation, and affects phosphorylation of STAT3 by activating SIRT1 in SW1353 chondrosarcoma cells." (PMID 36430164, 2022). "Sirt1 activation by Rsv also induces human chondrosarcoma cell apoptosis through intrinsic apoptotic pathways." (PMID 31817453, 2019). "In order to explore the potential mechanism that SIRT1 regulate the migration and invasion of chondrosarcoma cells, we performed RT-PCR and immunofluorescence staining to examine EMT-associated markers in SW1353 and HS.819.T cells." (PMID 28112277, 2017). "Transfection of cells with SIRT1 siRNA specifically inhibited SIRT1 expression and SIRT1 activity in resveratrol-treated chondrosarcoma cells." (PMID 28600541, 2017). "In this study, we observed the potentialeffect of SIRT1 on regulating metastasis in chondrosarcoma cells in vitro and in vivo." (PMID 28112277, 2017). "We have known that SIRT1 can effectively regulate the migration and invasion of chondrosarcoma cells in vitro." (PMID 28112277, 2017). "A clinicopathological analysis showed that SIRT1 expression was significantly correlated with pelvis chondrosarcoma." (PMID 28112277, 2017). "Firstly, we examined the SIRT1 expression and the efficiency of the adenovirus vectors that we used to regulate SIRT1 expression in human chondrosarcoma cells, SW1353 and HS.819.T cell line." (PMID 28112277, 2017). "A clinicopathological analysis showed that SIRT1 expression was significantly correlated with the poor prognosis of pelvis chondrosarcoma." (PMID 28112277, 2017). "We examined the effect of resveratrol on the expression and activity of SIRT1 in human chondrosarcoma cells." (PMID 28600541, 2017). "In the present study, we found that resveratrol (5–100 μM) effectively increased the SIRT1 expression and activity in human chondrosarcoma cells." (PMID 28600541, 2017). "The correlations among SIRT1 expression, and survival time of patients with pelvis chondrosarcoma were assessed." (PMID 28112277, 2017). "In conclusion, we demonstrate for the first time that SIRT1 activation by resveratrol induces apoptosis in human chondrosarcoma cells through the deacetylation of p65-NF-κB protein and exhibits antitumor activity in a chondrosarcoma mouse xenograft model." (PMID 28600541, 2017). "Here, we investigated the role of SIRT1 induction by resveratrol in human chondrosarcoma cell growth and tumor progression." (PMID 28600541, 2017). "Then high expression of SIRT1 in chondrosarcoma is always correlated with a poor prognosis in pelvis chondrosarcoma patients." (PMID 28112277, 2017). "These prompted us to study the involvement of this key deacetylase, SIRT1, in the resveratrol-related anti-cancer activity in human chondrosarcoma cells." (PMID 28600541, 2017). "In our study, we found that regulating the expression of SIRT1 in chondrosarcoma cells will lead to the change of the metastatic plasticity of the cells." (PMID 28112277, 2017).